AK5 (adenylate kinase 5)
Description:
Nucleoside monophosphate (NMP) kinase that catalyzes the reversible transfer of the terminal phosphate group between nucleoside triphosphates and monophosphates. Active on AMP and dAMP with ATP as a donor. When GTP is used as phosphate donor, the enzyme phosphorylates AMP, CMP, and to a small extent dCMP. Also displays broad nucleoside diphosphate kinase activity.
Synonyms: AK6
Tractability: Small molecule: a structure with a bound ligand is known; it has a binding pocket of medium quality. PROTAC: its protein half-life has been measured.
Gene: Protein-coding gene on chromosome 1 (77,282,019 to 77,559,966, forward strand). Ensembl gene ENSG00000154027.
Subcellular location: Cytoplasm
Subcellular location (Human Protein Atlas): Cytosol; Centriolar satellite
Pathways (Reactome):
Metabolism: Interconversion of nucleotide di- and triphosphates
Gene Ontology:
Molecular function: AMP kinase activity; nucleoside diphosphate kinase activity; ATP binding; nucleobase-containing compound kinase activity
Biological process: ADP biosynthetic process; dADP biosynthetic process; pyrimidine ribonucleotide biosynthetic process; ATP metabolic process; nucleobase-containing small molecule metabolic process
Cellular component: cytoplasm; cytosol
Genetic constraint (gnomAD): Loss-of-function variants: 17 observed, 50.97 expected, observed/expected ratio (o/e) 0.33, 90% interval 0.23 to 0.5. The upper end of that interval is the gene's LOEUF score, 0.5, which puts it in group 2 of 6, group 1 being the genes least tolerant of losing a copy. Missense variants: 435 observed, 607.33 expected, observed/expected ratio (o/e) 0.72, 90% interval 0.66 to 0.77. Synonymous variants: 227 observed, 218.64 expected, observed/expected ratio (o/e) 1.04, 90% interval 0.93 to 1.16.
Homologues: Orthologues: chimpanzee AK5 (99% identical), macaque AK5 (95% identical), dog AK5 (95% identical), mouse Ak5 (91% identical), rat Ak5 (89% identical), pig AK5 (88% identical), rabbit AK5 (85% identical), guinea pig AK5 (78% identical), tropical clawed frog ak5 (72% identical), zebrafish ak5l (33% identical), Caenorhabditis elegans F13E6.2 (22% identical), Drosophila melanogaster CG9541 (19% identical). Paralogues in human: AK9 (14% identical), AK8 (13% identical), AK1 (12% identical), CMPK1 (12% identical), AK7 (12% identical), AK2 (11% identical), AK4 (10% identical), AK4P3 (10% identical), AK3 (10% identical).